C16orf54 (chromosome 16 open reading frame 54)
Synonyms: FLJ35681; SAIL
Tractability: Antibody: UniProt predicts a signal peptide or a membrane-spanning region. PROTAC: ubiquitination databases record sites on it.
Gene: Protein-coding gene on chromosome 16 (29,742,463 to 29,745,990, reverse strand). Ensembl gene ENSG00000185905.
Subcellular location: Membrane
Gene Ontology:
Molecular function: protein binding
Cellular component: membrane
Genetic constraint (gnomAD): Loss-of-function variants: 2 observed, 5.49 expected, observed/expected ratio (o/e) 0.36, 90% interval 0.15 to 1.14. That is too few expected variants to judge how well the gene tolerates losing a copy. Missense variants: 272 observed, 251.15 expected, observed/expected ratio (o/e) 1.08, 90% interval 0.98 to 1.2. Synonymous variants: 128 observed, 98.71 expected, observed/expected ratio (o/e) 1.3, 90% interval 1.12 to 1.5.
Homologues: Orthologues: chimpanzee C16H16orf54 (98% identical), macaque C20H16orf54 (92% identical), dog C16orf54 (76% identical), mouse AI467606 (72% identical), guinea pig C16orf54 (71% identical), rat C1h16orf54 (56% identical).
Diseases named in the same sentence as C16orf54 in open-access papers:
C16orf54 is named in the same sentence as 32 diseases in open-access papers, as found by Europe PMC text mining. Sharing a sentence is not in itself a finding about the gene and the disease. The quoted sentences say what the papers report.
sarcoma (3 papers, 2015 to 2022). A usually aggressive malignant neoplasm of the soft tissue or bone. "Furthermore, this study identified specific molecules (C16orf54, CCR8, CYTIP, SAMD3 and TBX21) that can be used as predictors of the risk of progression and therapeutic targets for patients with sarcomas." (PMID 36153483, 2022). "Furthermore, we reveal five targetable antigens (C16orf54, CCR8, CYTIP, SAMD3 and TBX21) by identifying modules associated with the sarcoma immune landscape." (PMID 36153483, 2022). "Cox proportional hazards regression model analysis confirmed that high C16orf54 expression was related to poor OS in LGG, LAML, pan-kidney cohort (KIPAN), and uveal melanoma (UVM), whereas low expression was associated with a poor prognosis in SKCM, SKCM-M, sarcoma (SARC), CESC, LUAD, LIHC, and OV." (PMID 36118669, 2022).
cholangiocarcinoma (1 paper, 2022). A carcinoma that arises from the intrahepatic biliary tree (intrahepatic cholangiocarcinoma) or from the junction, or adjacent to the junction, of the right and left hepatic ducts (hilar cholangiocarcinoma). "Forest plots of PFI revealed that high C16orf54 mRNA levels were associated with a poor prognosis in LGG and UVM while low levels were associated with a poor prognosis in LIHC, CESC, SKCM, SKCM-M, BRCA, LUAD, cholangiocarcinoma (CHOL), ACC, and SARC." (PMID 36118669, 2022).
metastatic tumors (1 paper, 2023). "In general, overexpression of the C4orf46, C9orf40, C17orf67 and C21orf58 gene of thymoma correlates with tumor immune cell infiltration and gene expression levels of C1orf162, C16orf54 and CXorf21 correlate with immune cell infiltration in many primary and metastatic tumors." (PMID 37373333, 2023).
tumor (5 papers, 2015 to 2023). "Additionally, C16orf54 expression was significantly associated with tumour heterogeneity indicators, such as tumour mutation burden (TMB) and microsatellite instability (MSI), and was significantly correlated with DNAss and RNAss tumour stemness indicators." (PMID 36118669, 2022). "This study found that C16orf54 expression was significantly negatively linked to TMB and MSI in five and ten tumour types, respectively, further suggesting that C16orf54 could potentially predict patient response to immunotherapy." (PMID 36118669, 2022). "The relationship between C16orf54 expression and immune cell infiltration levels in different tumour types was evaluated utilizing the TIMER website tool." (PMID 36118669, 2022). "This study observed that C16orf54 expression was negatively correlated with DNAss in most tumours, such as THYM, GBM, and LUSC; similarly, it was significantly negatively correlated with RNAss in all tumours except THYM." (PMID 36118669, 2022). "C16orf54 is a protein-coding gene with heterogeneous expression in different normal and tumour tissues." (PMID 36118669, 2022). "This indicates low C16orf54 expression corresponds to strong tumour cell stemness, thus promoting tumour proliferation and metastasis." (PMID 36118669, 2022). "Among them, low C16orf54 expression was considered to be a risk factor for SKCM, LUAD, CESC, and other tumours." (PMID 36118669, 2022). "On the other hand, C16orf54 was reported to be negatively correlated with tumour purity in most cancers." (PMID 36118669, 2022). "The correlation analysis between C16orf54 expression and TME affirmed that C16orf54 expression was significantly positively associated with the three microenvironment scores of most tumours and negatively correlated with tumour purity, suggesting that C16orf54 affects the TME." (PMID 36118669, 2022). "Furthermore, the function of C16orf54 in the modulation of the tumour immune microenvironment (TIME) was investigated." (PMID 36118669, 2022). "The relationship between C16orf54 and tumour stemness was also analysed." (PMID 36118669, 2022). "Furthermore, evaluating the association between C16orf54 expression and OS, DSS, DFI, and PFI showed that C16orf54 expression was related to the prognosis of many tumours." (PMID 36118669, 2022). "Reports on the function of C16orf54 in the onset and development of tumours remain scarce." (PMID 36118669, 2022). "Therefore, enrichment analyses showed that the C16orf54 gene could participate in the occurrence and progression of tumours via the mechanism of the regulation of immune cell infiltration and immune regulatory factor-related signalling pathways." (PMID 36118669, 2022). "Therefore, C16orf54 expression in various tissues and tumours is heterogeneous." (PMID 36118669, 2022). "Expression profile and immunohistochemical results analysis showed that C16orf54 expression in BLCA, BRCA, COAD, LUAD, LUSC, and other tumour tissues decreased significantly, suggesting that C16orf54 could play a role in the occurrence and development of different tumours." (PMID 36118669, 2022). "In addition, C16orf54 and hepcidin antimicrobial peptide (HAMP) expression levels were both correlated with prognosis in four tumor types, except KIRC and BRCA, and 17 DEGs had expression levels associated with prognosis in three tumor types." (PMID 32903590, 2020). "This suggests that C16orf54 may regulate homeostasis of cell energy supply and cell membrane and thereby affect the crosstalk between various cells in the TME of various tumours." (PMID 36118669, 2022). "Furthermore, the link between C16orf54 expression and tumour immune microenvironment (TIME), tumour heterogeneity, and stemness are analysed." (PMID 36118669, 2022).
cancer (4 papers, 2015 to 2023). A tumor composed of atypical neoplastic, often pleomorphic cells that invade other tissues. "In this study, multiple bioinformatics tools are used to integrate multiple multiomics high-throughput data, such as TCGA data, to analyse the differential expression of C16orf54 and its prognostic and diagnostic roles in pan-cancer." (PMID 36118669, 2022). "The integrated analysis of C16orf54 indicates it as a potential prognostic, diagnostic, and immune marker, which could be adopted as a novel target for adjuvant immunotherapy across pan-cancer." (PMID 36118669, 2022). "The findings ascertained that C16orf54 was expressed at a low level in most cancers." (PMID 36118669, 2022). "C16orf54 expression was analysed across pan-cancer and normal tissues." (PMID 36118669, 2022). "Additionally, the possible molecular mechanism of C16orf54 across pan-cancer is elucidated using Kyoto Encyclopaedia of Genes and Genomes (KEGG) analysis and Gene Set Enrichment analysis (GSEA)." (PMID 36118669, 2022). "Furthermore, C16orf54 could distinguish between cancer and normal tissues with high accuracy in most cancers, and the prognostic significance of low C16orf54 mRNA levels differs across cancers." (PMID 36118669, 2022). "Further, C16orf54 expression was positively correlated with immune cell infiltration and the expression of immune regulatory genes, including chemokines, receptors, major histocompatibility complexes, immune inhibitory, and immune stimulatory genes, in most cancers." (PMID 36118669, 2022). "Though the functions of C16orf54, RARRES3, and TBC1D10C in cancer development have also been previously studied, their roles in NPC are revealed for the first time in this study." (PMID 37766321, 2023). "Then, we explored the TTK, C16orf54, PPAT, CD3EAP, SLCO2A1, ACAT1, and GAS2L3 genes in the CBioPortal for cancer genomics." (PMID 33402113, 2021). "Furthermore, the Pearson's correlation analysis of C16orf54 and immunoregulatory genes, including 41 chemokine, 18 receptor, and 21 major histocompatibility complex (MHC), showed that C16orf54 was significantly positively coexpressed with most immunomodulatory genes across pan-cancer." (PMID 36118669, 2022).
C16orf54 also shares sentences with these, for which no sentence is quoted: acute myeloid leukemia (1 paper); autism (1); B-cell lymphomas (1); bladder urothelial carcinoma (1); chronic lymphocytic leukemia (1); colon adenocarcinoma (1); diffuse large B-cell lymphoma (1); endometrial cancer (1); follicular lymphoma (1); glioblastoma (1); head and neck squamous cell carcinoma (1); hematologic cancers (1); hematologic malignancies (1); hematologic tumors (1); leukemia (1); liver cancer (1); lung adenocarcinoma (1); lung carcinoma (1); lung squamous cell carcinoma (1); lymphoma (1); ovarian carcinoma (1); Pan (1); rectum adenocarcinoma (1); thymoma (1); thyroid cancer (1); uterine corpus endometrial carcinoma (1); uveal melanoma (1).